INS (insulin)
Diseases named in the same sentence as INS in open-access papers (continued):
Sharing a sentence is not in itself a finding about the gene and the disease.
Obesity (continued). "In cases of T2DM or obesity, where chronic elevation of insulin leads to continued increases in lipid synthesis, mechanistic findings indicate that cellular INSIG levels were reduced." (PMID 33440724, 2021). "Obesity and overweight are the main predictors to T2D development, a metabolic disease that relies on defective insulin signaling." (PMID 34444990, 2021). "APBB1IP is commonly known as Rap1-GTPase, and plays a vital function in diet-induced obesity, insulin, and leptin resistance." (PMID 33669862, 2021). "It has been reported that the circulating level of adiponectin is lowered in obesity, and adiponectin treatment decreases hyperglycemia and improves insulin sensitivity by acting on skeletal muscle and the liver." (PMID 34199668, 2021). "This review summarizes in vitro and in vivo studies providing data related to the effects of flavonoids and flavonoid-rich foods on the modulation of the insulin route during T2D and obesity." (PMID 34208379, 2021). "Metabolic syndrome (MetS) is a multifaceted disease characterized by impaired insulin metabolism and glucose tolerance, obesity in the abdominal area, dyslipidemia, and hypertension." (PMID 34819073, 2021). "In human cohorts, CLS-B positively correlates with older age, obesity, dyslipidemia and higher levels of glucose, insulin, C-reactive protein and IL-6." (PMID 34294716, 2021). "Elevated PPARG activity is related to a higher incidence of obesity and impaired insulin signaling, two contributing factors to AD." (PMID 33920138, 2021). "These three isozymes can impact obesity etiology through NO production that plays essential roles in regulating adiposity, energy expenditure, and insulin sensitivity." (PMID 33924357, 2021). "Results of our caloric restriction study contradict some key concepts of the carbohydrate-insulin model (CIM) of obesity which has been advocated by some and criticized by others." (PMID 34578880, 2021). "Circulating fatty acids are increased in obesity as a result of the enlarged adipose tissue and resistance to the antilipolytic effect of insulin." (PMID 34201844, 2021). "Increased insulin and leptin resistance in obesity is manifested as a proportional rise in fasted and stimulated blood concentrations of both hormones as a function of increased body fat." (PMID 34836068, 2021). "The main PSG values worsen along with the increasing insulin resistance in both children with simple obesity and patients with PWS treated with rhGH." (PMID 33670584, 2021). "Female subjects had lower markers of obesity (i.e., BMI, waist-to-hip ratio), glucose homeostasis (i.e., fasting glucose, fasting insulin, HbA1c), blood pressure, albuminuria, interleukin﻿-6, and liver enzymes compared to male participants (all p < 0.05)." (PMID 34488766, 2021). "This is in accordance with previous studies in two different transgenic mouse models where it has been shown that a reduction in plasma membrane sphingomyelins improves insulin sensitivity and ameliorates high‐fat induced obesity." (PMID 33417276, 2021). "The older “calorie in, calorie out” (CICO) or energy balance model is being challenged by the carbohydrate-insulin model (CIM) of obesity." (PMID 34557366, 2021). "The carbohydrate–insulin model of obesity is a good theory that can explain increased skeletal muscle lipid accumulation." (PMID 34209545, 2021). "Taking into consideration that IGFBP2 is a leptin-regulated antidiabetic factor that protects against obesity, we calculated linear correlations between this factor in circulation with insulin, glycemia, leptin, body weight and the percentage of VAT." (PMID 34975768, 2021). "Furthermore, the current results support the potential role of high insulin levels for atherogenic progression and that maybe obesity is rather a consequence than the actual risk factor for developing hyperinsulinemia and in the further course arteriosclerosis." (PMID 34746266, 2021).
Obesity (continued). "In addition, given that obesity is associated with insulin dysregulation, altered NAc excitatory transmission, cognitive deficits, and some psychiatric diseases, we also determined how high-fat diet-induced obesity alters insulin's ability to influence NAc excitatory transmission." (PMID 33514676, 2021). "Initially, the “two-hit theory” emerged where an accumulation of lipids due to a sedentary lifestyle, high fat diet, insulin resistance, and obesity act as the first hit." (PMID 34307250, 2021). "It is worth to note that adiponectin is able to improve insulin sensitivity, which resembles the therapeutic effects of adropin in animal models of diet-induced obesity." (PMID 34199277, 2021). "The role of insulin/IGF-1 signaling pathways in maintaining a differentiated phenotype of pancreatic islet β-cells and the development of obesity-associated DM II is discussed." (PMID 34208601, 2021). "The downregulation of autophagy was observed, particularly in autophagy-related 7 (Atg7) expression levels in both genetic and dietary models of obesity, and in vivo and in vitro suppression of Atg7 led to impaired insulin signaling." (PMID 35392577, 2021). "SCFAs bind with G protein-coupled receptors and affect the expression of intestinal hormones, which act with various insulin-sensitive tissues, which consequently leads to an improvement in obesity and a reduction in WC." (PMID 33859706, 2021). "It is also known that the ROS are generated through excessive substrates provided by a high calorie diet that directly impair insulin signaling in obesity." (PMID 34690698, 2021). "The abundance of transcripts of HSD11B1, HSD11B2, PER1, and NR3C1 were unaffected by obesity or insulin." (PMID 33270115, 2021). "On a high fat diet, there is reduced hepatic lipogenesis, increased mitochondrial biogenesis, enhanced hepatic fatty acid (FA) oxidation, protection from obesity, and preserved insulin sensitivity." (PMID 35822025, 2021). "The numbers of Treg cells were strikingly and specifically reduced in insulin-resistant models of obesity." (PMID 33472506, 2021). "That observation supports the current findings, suggesting a major role for insulin and ghrelin cell–expressed IRs in regulating ghrelin secretion in the setting of diet-induced obesity." (PMID 34473648, 2021). "Macrophages, are of particular interest given that they exhibit increased infiltration into WAT during obesity and impact insulin sensitivity and glucose homeostasis, and these cells display decreased autophagic flux in insulin-resistant mice." (PMID 34336862, 2021). "The study cohort included 57 lean and healthy subjects (58.8%), 15 subjects with class 1 obesity (15.5%; BMI 33.7 ± 1.2 kg/m2), and 25 persons with T1D on insulin replacement who were otherwise healthy (25.8%)." (PMID 34075130, 2021). "The induction of Pparγ expression by the small molecule harmine improves insulin sensitivity with little effect on weight gain, suggesting that inducing Pparγ expression can be used against obesity related insulin dysfunctions." (PMID 33804020, 2021). "In the same study, administration of anti-resistin antibodies improved blood sugar and insulin action in mice with diet-induced obesity." (PMID 34069293, 2021). "Although GLUT4 level is moderately decreased in skeletal muscle of obese rodents, impaired insulin-dependent GLUT4 translocation in this tissue is considered as one of the main reasons for obesity-induced insulin resistance." (PMID 34907199, 2021). "The study results indicate that in obesity, high levels of insulin and IGF-1 enhance intestinal epithelial crypt proliferation through PI3K/AKT, without involvement of the ERK signaling pathway." (PMID 34659571, 2021). "Multivariate regression analysis also showed that salivary GSH depends on the severity of obesity measured by BMI and reduced insulin sensitivity expressed as HOMA-IR." (PMID 34557264, 2021).
Obesity (continued). "- ↓ diet-induced obesity, visceral fat and inflammation;- ↑ glucose tolerance, insulin sensitivity and intestinal integrity." (PMID 33693024, 2021). "Upregulation of mir-143 in dietary mouse models of obesity impairs insulin-stimulated AKT activation, through downregulation of oxysterol-binding protein-related protein 8 (ORP8) underlying the mechanism implicated in the obesity associated-IR." (PMID 34199293, 2021). "Insulin sensitivity and inflammation occur in SM in obesity by increasing immune cell infiltration and proinflammatory activation in intermyocellular and perimuscular adipose tissue." (PMID 33803198, 2021). "PTP1B-deficient mice are characterised by increased insulin sensitivity and are resistant to high fat diet (HFD)-induced obesity." (PMID 33893069, 2021). "ZAG has been shown to play a significant role in reducing obesity and improving insulin sensitivity, both in experimental animal model studies and in human studies." (PMID 34208404, 2021). "In the current study, HFD-induced obesity mice were used to investigate the effects of exercise training accompanied by dietary regulation on insulin sensitivity, macrophage phenotype, inflammation, and TRIB3-AKT signaling in adipose tissue." (PMID 34177606, 2021). "Then, we used a high-fat diet containing 10% lard to induce the metabolic characteristics of obesity in rabbits, such as increased subcutaneous and visceral fats, and significant differences in insulin and glucose levels in the obese group." (PMID 34698087, 2021). "Altogether, we propose the following model for insulin action in vivo on glycerol and fatty acids in obesity." (PMID 34321614, 2021). "LMO3 expression in eWAT significantly improved insulin sensitivity and healthy visceral adipose tissue expansion in diet-induced obesity, paralleled by increased serum adiponectin." (PMID 34018016, 2021). "IGF1 is a polypeptide that is structurally similar to human pro-insulin, which is one of the pathogenetic factors resulting in obesity and other diseases." (PMID 34544905, 2021). "Antibiotic treatment of mice with diet-induced obesity improves brain insulin signaling, neuroinflammation and depressive-like behavior, effects which are transferable to germ-free animals by fecal transplantation." (PMID 34201844, 2021). "Whole-body 11β-HSD1 reductase activity tended to be higher in obesity (~ 10%) and was further increased by insulin." (PMID 33270115, 2021). "Extensive metabolic dysregulation occurs during the process of obesity such as hyperglycemia, insulin insensitivity, abnormal metabolites, and high-density lipoprotein." (PMID 33763366, 2021). "In sheep models, fetuses of mothers with obesity have been shown to exhibit defects in skeletal muscle insulin signaling as well as increased fat accumulation and fibrosis." (PMID 34061777, 2021). "In the liver, there is a relevant pathway of Nrf2 restricted gluconeogenesis-related gene expression which plays a role in insulin sensitivity, maintenance of normal level of blood glucose and obesity prevention." (PMID 33468193, 2021). "In the case of obesity, there is a surplus of fats and glucose in the body which leads to increased insulin resistance." (PMID 33743677, 2021). "Obesity-initiated systemic or local inflammation and insulin resistance shift the AT secretome from an anti-inflammatory and anti-atherogenic state toward a pro-inflammatory and pro-atherogenic state." (PMID 34277732, 2021). "These mice were also resistant to HFD-induced obesity, due to increased energy expenditure with improved glucose and insulin tolerance." (PMID 34684670, 2021). "After 4 months of the experiment, the isocaloric HFD group did not a significant increase in body weight, while a higher body fat ratio and a state of obesity, along with increases in fasting plasma glucose and insulin concentrations were seen." (PMID 34208400, 2021). "These microbes have been shown to confer fuel to the intestine, prevent obesity and improve insulin sensitivity." (PMID 33744869, 2021).
Obesity (continued). "Obesity is diagnosed based on BMI in addition to changes in FFAs, and insulin levels, as well as vascular muscle tone and glucose levels." (PMID 34441691, 2021). "Circulating insulin reaches the striatum and NAc specifically, and diet-induced obesity is accompanied by chronic elevations in circulating insulin." (PMID 33514676, 2021). "Patients with T2DM and obesity are often characterized by long periods of elevated intrapancreatic insulin levels caused by the pancreatic β-cells trying to overcome the insulin resistance present in T2DM and obesity to maintain glucose homeostasis." (PMID 34680216, 2021). "These novel results indicate that repeated intake, rather than a single dose of NZBC extract, is required to induce beneficial effects on insulin sensitivity and postprandial glucose handling in individuals with overweight or obesity." (PMID 32648022, 2021). "Although obesity is a major risk factor of GDM, other factors such as insulin secretory defects contribute to the development of GDM which is evident among women with normal BMI." (PMID 33467738, 2021). "Curcumin, the primary natural polyphenolic compound of the spice turmeric, also has anti-insulin sensitivity and anti-obesity activity." (PMID 34371900, 2021). "Obesity plays a key role in developing abnormalities in sex hormone metabolism and insulin levels, as a result of the excessive accumulation of adipose tissue or body fat." (PMID 34530776, 2021). "While high expression of AZGP1 in Western diet mice agrees with its known functions in lipid degradation processes and impaired insulin sensitivity in obesity, AZGP1 was also suggested to be involved in bitter taste perception by Gene Ontology analyses." (PMID 34066295, 2021). "The main biologic mechanisms whereby physical activity, sedentary behavior, and obesity are related to cancer incidence include an effect on endogenous sex steroids and metabolic hormones, insulin sensitivity, and chronic inflammation." (PMID 32741068, 2021). "For instance, white adipocytes contribute to WAT expansion via hyperplasia and hypertropia during obesity, whereas the activation of brown adipocytes and the induction of beige adipocytes reduce obesity and improve insulin sensitivity." (PMID 34108967, 2021). "In obesity, Os also inhibits mitochondrial function, resulting in Lptx, which impairs insulin signaling (a powerful anabolic signal), promotes high catabolism (which induces muscle mass loss), and leads to IR and inflammation." (PMID 34676021, 2021). "From the selected articles, 39 of them focused on obesity and 2 articles on T2DM, although 7 articles from obesity included glucose and insulin levels in their main research parameters." (PMID 33579237, 2021). "Very interestingly, ML‐inulin administration was shown more effective than that of S‐inulin in HFD‐induced obesity, inflammation and insulin sensitivity." (PMID 34262707, 2021). "Obesity is a heterogeneous disease characterized by considerable fluctuations in fat distribution, inflammation, muscle density, and insulin resistance, among others." (PMID 34421889, 2021). "On the other hand, a study with 507 youths (age 8–16 years) with T1D from four separate cohorts showed that the prevalence of overweight status or obesity was 33% and remained stable over a decade despite increased implementation of intensive insulin therapy." (PMID 34638531, 2021). "CTRP-2 knock-out mice showed elevated energy expenditure, and upregulation of lipolytic enzymes whereas CTRP-2 transgenic mice subjected to diet-induced obesity showed improved lipid and insulin tolerance." (PMID 33874963, 2021). "IR also underlies many obesity-related malignancies, through the effects of compensatory hyperinsulinaemia on the relatively intact MAP-K insulin pathway, which controls cellular growth processes and mitoses." (PMID 33430419, 2021).
Obesity (continued). "Of note, protective effects of BA composition on WTD-induced obesity, insulin sensitivity, and hepatic steatosis have also been described in Cyp8b1−/− mice." (PMID 34626589, 2021). "Leptin and insulin are equally important in the metabolic features of the pathophysiology of obesity, and PREP1 plays a primary role in organogenesis and metabolism." (PMID 34327205, 2021). "Functional studies in mice have demonstrated that Camk2b−/− are susceptible to obesity and that the enzyme Camk2b is translated into, CaMKII, is involved in the hepatic insulin resistance that occurs with obesity." (PMID 34849860, 2021). "Metformin is a biguanide molecule used as an oral insulin-sensitising drug for the treatment of metabolic disorders, such as type 2 diabetes, obesity, insulin resistance and polycystic ovary syndrome (PCOS)." (PMID 34745014, 2021). "In summary, skeletal muscle expressed GPCRs represent promising therapeutic targets for modulating insulin sensitivity and treating T2D and obesity-related metabolic disorders." (PMID 34497585, 2021). "The physiological mechanisms driving obesity-induced β cell expansion include increased plasma glucose concentrations, insulin, expression of hepatocyte growth factors, and islet macrophage-mediated islet inflammation." (PMID 34572101, 2021). "Nevertheless, we found strong correlations between SHBG and insulin plasma levels when analyzing our study population or children with obesity alone." (PMID 33689083, 2021). "Obesity-induced low-grade inflammation decreases insulin signaling which results in IR in liver and skeletal muscles." (PMID 34844584, 2021). "Reduced insulin sensitivity correlates with elevated levels of circulating chemocytokines for example, TNF-α, IL-6 and IL-8 that trigger obesity-associated metabolic inflammation." (PMID 35128441, 2021). "Alterations in substrate oxidation do not appear to be the mechanism by which four weeks of SIT improves insulin sensitivity in individuals living with obesity." (PMID 34110721, 2021). "To determine the role of brown fat UTX in the regulation of diet-induced obesity, we conducted metabolic characterization of body weight, energy metabolism and insulin sensitivity in UTXKO mice fed a high-fat diet (HFD)." (PMID 34824202, 2021). "This shift in the insulin : GH ratio blocks lipid breakdown and promotes further energy storage and lipid synthesis, resulting in obesity due to more fat accumulation and a lower energy expenditure." (PMID 34360563, 2021). "Nevertheless, our findings provide novel insights into the effects of lifestyle intervention on branched‐chain amino acid catabolism and insulin sensitivity in adolescents with obesity." (PMID 34277974, 2021). "In contrast, this study focuses on obesity and insulin‐resistant conditions, which are accompanied by excessive Drp1 activity (e.g., Drp1 phosphorylation)." (PMID 33904649, 2021). "The study provides new insight into the mechanism of metformin action in insulin sensitization and obesity." (PMID 34659115, 2021). "Blautia, a beneficial bacterium in the gut, inhibits insulin signaling and fat accumulation by the activation of G protein-coupled receptors GPR41 and GPR43, attenuating the diseases associated with obesity." (PMID 34681506, 2021). "Regular physical exercise is well known to reduce inflammation resulting from obesity and, consequently insulin resistance in both peripheral and central tissues." (PMID 34203825, 2021). "Mice deficient of Flt3l (Fms-related tyrosine kinase 3 ligand) show a lack of DCs as well as reduced amounts of natural killer cells and regulatory T cells and B cells, while insulin sensitivity in diet-induced obesity is improved." (PMID 34357044, 2021). "Correspondingly, mice with SRA knockout displayed resistance to obesity caused by a high-fat diet (HFD), decreased adipose tissue mass and gene expression of adipocytes, reduced plasma TNFα, and enhanced insulin sensitivity." (PMID 33800718, 2021).